IL1B (interleukin 1 beta)
Diseases named in the same sentence as IL1B in open-access papers (continued):
Sharing a sentence is not in itself a finding about the gene and the disease.
cryopyrin-associated periodic syndrome (continued). "Cryopyrin-associated periodic syndrome (CAPS) is a rare autoinflammatory disorder associated with overproduction of IL-1β." (PMID 23421920, 2013). "Using this system, the expression of NLRP3 mutants in cryopyrin-associated periodic syndrome (CAPS) patients was sufficient for the induction of necrotic cell death without lipopolysaccharide stimulation or generation of mature IL-1β." (PMID 23703389, 2013). "Cryopyrin-associated periodic syndrome (CAPS) is a rare inherited inflammatory disorder with a unique pathophysiology related to overproduction of interleukin-1-beta (IL-1β)." (PMID 22348744, 2012). "IL-1Ra inhibits the activity of both IL-1α and IL-1β and is clinically approved as the drug anakinra for treating autoimmune disorders such as cryopyrin-associated periodic syndrome (CAPS), Still’s disease, familial Mediterranean fever (FMF), rheumatoid arthritis, and periodic fever syndromes." (PMID 41301455, 2025). "Therefore, IL-1β is closely related to various autoinflammatory diseases, including gout, familial Mediterranean fever, cryopyrin-associated periodic syndrome (CAPS), AOSD, and systemic JIA." (PMID 39062908, 2024). "Canakinumab is a fully human anti-IL-1β-antibody which has indication for systemic JIA and cryopyrin-associated periodic syndromes (CAPS)." (PMID 33634341, 2021). "Although, to date, no reports have investigated the expression of the NLRP3 inflammasome in brain mast cells, peripheral tissue mast cells from cryopyrin-associated periodic syndrome (CAPS) patients were, for the first time, shown to express functional inflammasomes and secrete IL-1β." (PMID 33499208, 2021). "Indeed, some patients suffering cryopyrin-associated periodic syndromes (CAPS) such as NOMID appear resistant to IL-1β blocking agents." (PMID 32104502, 2020). "In addition, the IL-1β antagonist antibody ACZ (canakinumab) has been approved for treating cryopyrin-associated periodic syndromes (CAPS)." (PMID 28927416, 2017). "In a case report, celiac disease was found in patients with cryopyrinopathies suggesting the likelihood of excessive IL-1β production in the generation of reactive T cells that can promote the pathophysiology of celiac disease." (PMID 25788762, 2015). "In a recent clinical trial for the inflammasome-mediated disease, Cryopyrin-associated periodic syndrome (CAPS), patients receiving the humanized monoclonal antibody, canakinumab, specific for IL-1β, had a 67% increased risk for infection compared to 25% of patients in the placebo group." (PMID 25010102, 2014). "HRQoL was examined during a treatment trial of the cryopyrin-associated periodic syndromes (CAPS) using canakinumab, an IL-1β antibody." (PMID 25147819, 2014). "The cryopyrin-associated periodic syndromes (CAPS) are usually caused by heterozygous NLRP3 gene variants, resulting in excessive inflammasome activation with subsequent overproduction of interleukin (IL)-1β." (PMID 33401496, 2021). "Cryopyrin-Associated Periodic Syndrome (CAPS) represents autosomal dominant gain of function mutations that results in over activation of the inflammasome and increased conversion of pro-caspase-1 to activate caspase-1 and this results in increased IL-1β and IL-18 protein levels." (PMID 35003136, 2021). "In the chronic diseases driven by inflammation, such as type 2 diabetes and cryopyrin-associated periodic syndromes (CAPS), the NLRP3 inflammasome is dysregulated, resulting in the uncontrolled release of pro-inflammatory cytokine IL-1β, which drives inflammation in such diseases." (PMID 34439904, 2021). "Cryopyrin-associated periodic syndromes (CAPS) are a group of rare, monogenic, autoinflammatory diseases caused by a gain of function mutation in NLR family pyrin domain containing 3 (NLRP3), which results in excess production of interleukin-1 beta (IL-1β)." (PMID 31287007, 2019).
cryopyrin-associated periodic syndrome (continued). "The NLRP3 inflammasome gained a lot of attention due to the causality of NLRP3 mutations in cryopyrin-associated periodic syndromes (CAPS), an auto-inflammatory pathology characterized by high levels of IL-1β secretion from peripheral blood mononuclear cells (PBMCs) of patients." (PMID 28403163, 2017). "In the IL-1β-mediated autoinflammatory diseases Cryopyrin Associated Periodic Syndrome (CAPS) and Schnitzler Syndrome (SchS), non-itchy urticarial rash is a hallmark symptom." (PMID 28078079, 2017). "Cryopyrin-associated periodic syndromes are disorders caused by mutations in the NLRP3 gene, previously known as cold-induced autoinflammatory syndrome 1, which results in uncontrolled processing of IL-1β and IL-18." (PMID 28588486, 2017). "Inflammasome activation leads to efficient defense against pathogens, while missense mutations in the NLRP3 protein-encoding gene (Cias1) cause autoinflammatory disorders cryopyrinopathies (i.e. cryopyrin-associated periodic syndromes, CAPS), where IL-1β is constitutively processed." (PMID 27467658, 2016). "Indeed, in patients with cryopyrinopathies, caused by gain of function NLPR3-mutations, increased IL-1β release following stimulation with LPS alone is a typical feature of the disease." (PMID 25061439, 2014). "SchS shares many features with the hereditary autoinflammatory syndrome cryopyrin-associated periodic syndrome (CAPS), which is caused by NLRP3 mutations that lead to enhanced IL-1β production that induces chronic systemic inflammation, including fever and joint pain." (PMID 25905009, 2014). "Indeed Lasiglie analyzing 11 patients carrying this mutation (Cryopyrin-associated periodic syndromes, CAPS) observed a skewed Th17 phenotype in PB lymphocytes, as well as an increased production of IL-1β and IL-23 by monocyte-derived dendritic cells." (PMID 23874332, 2013). "Cryopyrin-associated periodic syndrome (CAPS) is an autoinflammatory disease caused by a gain-of-function mutation in the NLRP3 gene, which regulates inflammasome-mediated interleukin-1β (IL-1β) production." (PMID 40927711, 2025). "For instance, Cryopyrin-associated periodic syndromes (CAPS) are caused by gain-of-function mutations in the NLRP3 gene that result in the constitutive activation of the NLRP3 inflammasome and the release of IL-1β, in turn responsible for the symptomatology of the disease." (PMID 32796686, 2020). "Cryopyrin-associated periodic syndromes (CAPS) are caused by a mutation in NLRP3 inflammasome, resulting in increased IL-1β and IL-18 production, but impaired production of the anti-inflammatory IL-6 and IL-1RA cytokines." (PMID 29515591, 2018). "These three diseases are collectively known as cryopyrin-associated periodic syndrome (CAPS), suggesting that the disease-associated variants of NLRP3 probably encode a hyperactive version of NLRP3 which promotes excessive production of IL-1β." (PMID 29850543, 2018). "Also, in patients affected by cryopyrin-associated periodic syndrome (CAPS), a group of rare autoinflammatory diseases with genetic basis, the levels of IL-1β are fivefold higher than in healthy individuals, leading to persistent unregulated systemic inflammation." (PMID 28347403, 2017). "Cryopyrin-associated periodic syndromes are a group of autoinflammatory diseases transmitted by autosomal dominant inheritance caused by mutations in the NLRP3 gene (also called CIAS1 or PYPAF) encoding for cryopyrin, a crucial inflammasome protein that directly activates IL-1β." (PMID 24282415, 2013). "The extracellular portion has a strong affinity for both IL-1α and IL-1β, thereby neutralising their activities and functioning as an “IL-1 trap”.127,128 It was approved by the FDA in 2008 for the treatment of cryopyrin-associated periodic syndromes (CAPS)." (PMID 31900383, 2020).
cryopyrin-associated periodic syndrome (continued). "A more recent paper on the rare disease cryopyrin-associated periodic syndromes (CAPS, caused by NLRP3 mutations and consequent overproduction of IL-1β) suggested that MDSCs might act in an anti-inflammatory manner and exert beneficial effects." (PMID 31156644, 2019). "The effect of OME on IL-1β secretion was investigated on monocytes from patients affected by cryopyrin-associated periodic syndrome (CAPS), a very rare autoinflammatory disease where gain-of-function mutations in the inflammasome gene NLRP3 cause huge secretion of IL-1β." (PMID 27441656, 2016). "The family of cryopyrin-associated periodic syndrome (CAPS) is linked with mutations in the NLRP3 gene, encoding a structurally crucial inflammasome protein, named cryopyrin, which directly controls the release of bioactive IL-1β." (PMID 26357457, 2015). "Among the autoinflammatory syndromes, cryopyrin-associated periodic syndromes (CAPS) are conditions associated with mutations of the NLRP3 gene, also known as CIAS1 or PYPAF1, a key component of the inflammasome directly involved in the mechanism of interleukin-1β (IL-1β) processing and secretion." (PMID 21360512, 2011). "However, in most IL-1–related autoinflammatory conditions, such as cryopyrin-associated periodic syndromes (CAPS), no mutations exist in the IL1RN or IL1B genes." (PMID 40668918, 2025).
tuberculosis (108 papers, 2007 to 2026). A chronic, recurrent infection caused by the bacterium Mycobacterium tuberculosis. "In contrast, the T allele is associated with increased IL-1β expression, which heightens the risk of tuberculosis." (PMID 40506975, 2025). "In a cohort of 88 newly diagnosed CPA patients, AECOPD and active tuberculosis were associated with heightened pro-inflammatory responses and elevated IL-1β levels; an IL-1β concentration >20.3 pg/mL was defined as “high”." (PMID 41209007, 2025). "Recent studies have indicated that decreased levels of IL‐1β are associated with the development of severe tuberculosis symptoms." (PMID 39240051, 2024). "A naturally occurring polymorphism in the human IL1B promoter region that leads to high IL-1β production is associated with the development of active tuberculosis, disease severity, and poor treatment outcome." (PMID 35173157, 2022). "The high IL-1β expressing rs1143627TT genotype was associated with the severity of lung pathology in TB patients both before and after anti-tuberculosis treatment." (PMID 25329476, 2014). "The high-IL-1β-expressing genotype is associated with increased risk of active tuberculosis and poor clinical outcome." (PMID 25329476, 2014). "An association between IL-1β and the resistance to tuberculosis was inferred from human IL-1B gene polymorphism." (PMID 25400917, 2013). "In single locus association testing of each polymorphism among all study participants, the IL-1β +3953 (C→T) SNP was associated with any tuberculosis (P = 0.044) and extrapulmonary tuberculosis (P = 0.049) compared to PPD+ controls." (PMID 20196868, 2010). "In single locus association tests among genetic variants previously associated with tuberculosis susceptibility, IL-1β +3953 was associated with extrapulmonary disease, as well as all forms of tuberculosis, compared to persons with M. tuberculosis infection." (PMID 20196868, 2010). "This suggests that tuberculosis-associated systemic inflammation may exacerbate organ dysfunction through a TNF-α/IL-1β positive feedback loop, providing new insights for precise interventions in comorbid populations." (PMID 40831574, 2025). "The analysis of single nucleotide polymorphisms (SNP) in the human IL1B gene identified 3 SNPs in the genes promoter region that results in increased IL-1β expression and was associated with more severe tuberculosis possibly due to the increased infiltration of neutrophils." (PMID 35237260, 2022). "In addition to the assumed pathogenic role of IL10 in tuberculosis disease progression, the protective roles of the pro-inflammatory cytokines TNFα and IL1β have been well documented by in vivo murine models, and for IL1β in hMDMs." (PMID 32477344, 2020). "Interestingly and contradictorily, a previous study has discovered a high IL-1b expressing genotype, which was associated with the development of active tuberculosis, higher disease severity, and poorer treatment outcome in TB patients." (PMID 31781307, 2019). "This cytokine has been implicated in HAD and has been shown to be highly expressed in patients with HAD, and increased production of IL-1β following monocyte activation with toll-like receptor (TLR) ligands has been associated with reduced odds of tuberculosis recurrence." (PMID 29394269, 2018). "The impaired IL-1β production in T1D patients may contribute to the increased susceptibility to tuberculosis." (PMID 29189980, 2018). "The high-IL-1β expressing genotype was associated with the development of active tuberculosis, the severity of pulmonary disease and poor treatment outcome in TB patients." (PMID 25329476, 2014). "On the other hand, IL-1β and IL-6 participate in the formation of tuberculosis granulomas, regulate the activation of macrophages and T-lymphocytes, and influence the secretion of interferon-γ and other key cytokines." (PMID 40141021, 2025).
tuberculosis (continued). "The key cytokines and chemokines that play a role in the comorbidity of COPD and tuberculosis are interleukins 1β, 6, and 8 (IL-1β, IL-6, IL-8), TNF-α, and interferon gamma (IFN-γ)." (PMID 40141021, 2025). "In turn, in tuberculosis, IL-1β is involved in granuloma formation, thereby limiting the spread of M. tuberculosis in tissues." (PMID 40141021, 2025). "Studies of miR-708 in both macrophage-like and non-immune cell lines identified the roles of this miR in the regulation of tumor necrosis factor alpha/interleukin 1 beta, arachidonic acid pathways and inflammatory responses to mycobacterium tuberculosis." (PMID 38556087, 2024). "Neutrophils, key cells in tuberculosis, reach the lungs as two distinct subsets playing opposite roles in inflammation: either exacerbating via IL-1b or dampening via PD-L1." (PMID 38803236, 2024). "It is the case in tuberculosis, where it promotes M. tuberculosis infection by negatively controlling the secretion of IL-1β." (PMID 37428812, 2023). "It was shown in an investigation conducted on 681 patients with lung tuberculosis that the IL-1β blood concentration can be a predictive marker of tuberculosis severity." (PMID 37686061, 2023). "The success of the host anti-tuberculosis response depends on tight control of the expression of pro-inflammatory cytokines such as TNFα and IL1β." (PMID 36120339, 2022). "Nodal analysis revealed that IL-17A again had the greatest nodal connectivity in ART-naive participants with HIV–tuberculosis co-infection, with IL-1β and TNFα in second and third place." (PMID 34386782, 2021). "Inflammasome-derived cytokines, IL-1β and IL-18, and complement cascade have been independently implicated in the pathogenesis of tuberculosis (TB)-immune reconstitution inflammatory syndrome (TB-IRIS), a complication affecting HIV+ individuals starting antiretroviral therapy (ART)." (PMID 33788899, 2021). "Exploiting a clinical cohort of tuberculosis patients, we show here that the number and size of necrotic lesions correlates with IL-1β plasma levels as a strong indicator of inflammasome activation." (PMID 34718331, 2021). "At least with regard to the S‐protein, this pre‐activation step seems to be non‐specific as shown by S‐protein‐driven IL‐1β secretion in macrophages isolated from patients with active tuberculosis." (PMID 34133077, 2021). "Here the authors stratify patients by severity of tuberculosis and find correlations with the level of IL-1β production by macrophages exposed to these isolates." (PMID 32327653, 2020). "IL-1β production is significantly increased in tuberculosis pleurisy, which usually presents as a self-resolving type of primary tuberculosis." (PMID 29386556, 2018). "It is largely accepted that monoctyes and dendritic cells are the primary source of IL-1β in the lungs of tuberculosis-infected mice." (PMID 28747644, 2017). "Tuberculosis has also been shown to promote T helper-2 (Th 2) cell differentiation via IL-1β induction in the dendritic cells." (PMID 24839445, 2014). "Murine models of tuberculosis provide compelling evidence for the importance of IL-1β signalling in the host resistance to M. tuberculosis infection." (PMID 23849220, 2013). "Increased mRNA expression of IFN-γ TNF-α, IL-6, IL-8 and IL-12 in tuberculosis granuloma and secretion of cytokines IL-1β, TNF-α and IL-6 in bronchoalveolar lavage fluid from involved sites of pulmonary TB have been reported." (PMID 23308269, 2013). "Lower levels of IL-1β were detected in both diseases compared to healthy serum with significance in sarcoidosis and just below significance in tuberculosis (adjusted p = 0.059)." (PMID 22815689, 2012). "For example, IL1B has a protective role in immunity to tuberculosis and leads to the production of NO." (PMID 21629653, 2011). "IL-1β is upregulated in the lungs of tuberculosis patients, and both IL-1β and IL-18 are secreted from M. tuberculosis and M. marinum infected macrophages in vitro." (PMID 20463815, 2010).